CTLA4 (cytotoxic T-lymphocyte associated protein 4)
Diseases named in the same sentence as CTLA4 in open-access papers (continued):
Sharing a sentence is not in itself a finding about the gene and the disease.
tumor (continued). "Currently, a clinical trial (NCT03098160) is investigating the efficacy of TH‐302 in combination with ipilimumab (anti‐CTLA‐4) against a range of tumour types." (PMID 35466515, 2022). "PD-L1 expression was highly elevated on both tumor cells and macrophages in animals receiving anti-CTLA4 or combined immunotherapy (bottom row)." (PMID 36230753, 2022). "Tumor ROIs of short-term survivors revealed a high expression of molecules correlated with immune suppression such as PD-1, PD-L1, CTLA4, LAG3, FoxP3, and CD25 compared to long-term survivors." (PMID 36685537, 2022). "Immune checkpoint inhibitors target immune checkpoint molecules, primarily PD-1, PD-L1, and CTLA-4 to restore anti-tumor immune function." (PMID 36131911, 2022). "CTLA-4 blockade contributed to the CD28-mediated proliferation of tumor-associated Tregs, inducing tumor immune tolerance ultimately." (PMID 36335094, 2022). "James Alison’s team was the first to show that blocking the CTLA-4 signal with a monoclonal antibody (mAb) alone can promote tumor regression in a transplanted mouse tumor model." (PMID 35954362, 2022). "P407-hydrogel-based CTLA4 therapy resulted in equal tumor growth inhibition efficiency in both tumor models as the “free” CTLA4 blockade treatment, which is consistent with our previous in vitro data and our previous statement." (PMID 35974207, 2022). "The FOXP3HighCTLA4High* subpopulation (Treg subpopulation with overexpressed CTLA4) was characterized by an immune overdrive phenotype with high immune cell infiltration, low tumor purity, high IC levels, and TGF-β activation in CRC, and observed in LGG." (PMID 35812384, 2022). "In relation to negative regulation of anti-tumor immunity via IC expression, γδ T cells rarely express CTLA-4 but PD-1 can be expressed on activated cells, while TIM-3 expression has been shown to reduce the cytotoxicity of Vγ9Vδ2 T cells." (PMID 35804964, 2022). "CTLA-4-targeting agents can release the “brakes” off the immune system to promote anti-tumor immune responses." (PMID 35326731, 2022). "At the same time, the expression levels of cytokines and immunosuppressor molecules (PD1, PD-L1, PD-L2, CTLA4, TIGIT, TIM-3, BTLA, and LAG3) were significantly higher in low-risk groups, implying more tumor immunogenicity in the low-risk group." (PMID 36217201, 2022). "The combined use of anti-interleukin-6 and anti-CTLA-4 was found to promote antitumour activity via enhancement of T-cell tumour infiltration." (PMID 35626020, 2022). "We examined the expression differences of immune checkpoints (PD-1, PD-L1, and CTLA-4) in the two clusters and examined the differences between tumour and normal tissues." (PMID 35087586, 2022). "ICIs exert anti-tumor activity by reactivating host-specific cytotoxic T cells that are suppressed by the PD-1/PD-L1 and CTLA-4 pathways." (PMID 35740355, 2022). "Exhausted T cells not only highly express PD-1 and CTLA-4, but also highly express semaphorins and their receptors, especially Nrp-1; thus, tumor cells are compromised to immune checkpoint inhibitors and turn to self-tolerance." (PMID 35155237, 2022). "Despite the expected general link between high absolute numbers of CTLA-4+ cells and favorable tumor features, there were also some associations between a high CTLA-4/CD3-ratio and favorable tumor features." (PMID 35091676, 2022). "Here the authors show that tumor-expressed B7x promotes the conversion of conventional CD4+ T cells into regulatory T cells within the tumor microenvironment to promote immune evasion and resistance to anti-CTLA-4 therapy." (PMID 35523809, 2022). "The Treg-depleting effect of anti-CTLA-4 has been shown to be Fc-mediated, primarily by tumor-infiltrating macrophages (TAMs) expressing FcγRI and FcγRIV within the tumor microenvironment." (PMID 35523809, 2022).
tumor (continued). "There appears to be a decrease in the expression levels of CTLA-4 on the surface of tumour-infiltrating CD4+ T cells post-FLOT compared with the treatment-naïve setting (p = 0.07)." (PMID 35366537, 2022). "CTLA-4 was the first IC identified as a target to enhance T cell immunity in tumor-bearing mice and was also the first to be targeted therapeutically." (PMID 36612180, 2022). "The combination therapy (ICG-PDT-based combination with dual-ICI therapy (anti-CTLA4 and anti-PD-L1)) resulted in the strongest tumor growth inhibition and the highest percentage of tumor-free survival rate (62.5%)." (PMID 35974207, 2022). "In trials comparing the effects of high glycolysis tumours with low glycolysis tumours on CTLA-4 immunotherapy, the therapeutic effect of low glycolysis tumours is found to be more pronounced." (PMID 36569832, 2022). "TGFB1 stimulates the expression of CTLA4, thus aggravating CTLA4-related inhibition of t-cell proliferation and cytokines release and promoting t-cell apoptosis, which enables tumour immune escape." (PMID 36614082, 2022). "Previous studies have shown the FcγR-dependent activity of anti-mouse CTLA-4 antibodies in mouse tumor models." (PMID 34922008, 2022). "In this study, we addressed the effects of monotherapy and combination therapy using anti-PD-1 and anti-CTLA-4 therapeutic antibodies in graft mouse tumor models." (PMID 35339889, 2022). "Blockade of β-AR reduces tumor progression and upregulates the response to anti-CTLA4 therapy contributes to the formation of an immunosuppressive TME." (PMID 36072337, 2022). "Collectively, these data suggested that selective FcγR-mediated intratumoral Treg depletion was a driver in promoting anti-CTLA-4 antibody-mediated anti-tumor activity." (PMID 35237846, 2022). "We evaluated the therapeutic efficacy of combining anti–PD-1 and anti-CTLA4 antibodies in transplanted PRC2-isogenic AT3 tumor models." (PMID 35852856, 2022). "Mice treated with doxorubicin alone or combination treatment had lower expression of tumor PD-L1, CTLA-4, Foxp3, and tumor-infiltrating dendritic cell (CD86) proteins than did controls, with the lowest expression in mice co-treated with high-FO/Se." (PMID 36483592, 2022). "Since immune checkpoint blockade targeting PD-1, PD-L1 and CTLA4 has become an effective therapy to activate anti-tumor immunity, the application of this strategy to BC is drawing more and more attention." (PMID 35787661, 2022). "Combining anti-OX40 and anti-CTLA-4 immunotherapy boosted tumor regression and tumor-bearing host survival depending on CD4+ and CD8+ T cells." (PMID 35585567, 2022). "In tumor-bearing mice, the immune response was increased upon treatment with anti-tumor vaccines and, more efficiently, with a combination of anti-CTLA-4 plus anti-PD-L1 antibodies." (PMID 35922755, 2022). "The recolonization of Bacteroides fragilis in antibiotic-treated mice was previously observed to rescue CTLA-4 blockade resistance, and oral gavage of Bacteroides fragilis induced the Th1 immune response and DC maturation in the tumor-draining lymph node." (PMID 35682578, 2022). "Monoclonal antibodies that target the PD-1/PD-L1 (B7-H1) or B7-2/CTLA-4 pathways have been shown to be promising in promoting long-term tumor regression in a range of cancers." (PMID 35935979, 2022). "Combination therapy of anti-CTLA-4 with anti-GITR or anti-OX40 agonists induces a more robust anti-tumor immune response than any of these as single-agent therapies." (PMID 35326731, 2022). "Although both CTLA-4 and PD-1 exert an inhibitory immune response (including impact on tumor kinetics), the mechanism of action and the site of expression are significantly different." (PMID 35741331, 2022). "The other group of molecules responsible for causing dysfunction in tumour-infiltrating DCs are immune checkpoint proteins PD-L1, PD-1, ILT2, CTLA4, TIM3 expressed by tumour cells or other immune cells." (PMID 35355992, 2022).
tumor (continued). "As co-inhibitory receptors play a role in T cell exhaustion and are important targets for immune checkpoint-inhibition, we analyzed PD-1 and CTLA-4 expression on the tumor-specific CD39+ CTL population." (PMID 35740561, 2022). "Evaluation of this PET tracer in murine models demonstrated high uptake by tumours in response to anti-CTLA-4 treatment, which correlated with a subsequent reduction in tumour size." (PMID 36297474, 2022). "Together, these data clearly demonstrate an enhancing effect of targeting tumor sialylation and PD-1/CTLA-4 blockade." (PMID 36322632, 2022). "In other words, treatment with anti-CTLA-4 leads to the expression of PD-1 on the tumor cell surface." (PMID 36276117, 2022). "ICIs, such as anti-programmed cell death-1(PD-1), anti-programmed cell death-ligand 1 (PD-L1), and anti-cytotoxic T lymphocyte-associated antigen-4 (CTLA-4) made significant progress in amplifying endogenous anti-tumor T cell responses." (PMID 36233246, 2022). "Anti-CTLA-4 enhances T-cell priming against tumor antigens, while anti-PD-1 enhances the metabolism and effector function of tumor-specific progenitor exhausted T cells." (PMID 35463322, 2022). "The Food and Drug Administration (FDA) and the European Union have approved several immune checkpoint inhibitors and monoclonal antibodies for clinical tumor treatment, such as CTLA4 monoclonal antibody ipilimumab, PD1 monoclonal antibody nivolumab, etc.." (PMID 35449866, 2022). "We also computed survival models testing the relationship between the percent positivity of OX40L, CTLA4, and CD11c expression in both tumor and stroma samples with time to biochemical relapse." (PMID 36230846, 2022). "Boosting anti-tumor immunity can also be achieved by blocking T cell response inhibitory signals, commonly targeting sites including CTLA-4 and PD-1/PD-L1." (PMID 36341333, 2022). "We broadly profiled the tumor immune infiltrate and found that anti-CTLA-4 treatment generally increased effector T cell and NK cell populations in B7x+ and B7x− tumors." (PMID 35523809, 2022). "Since the expression of CTLA-4 and PD-1 were the highest in the exhausted T cell subgroup (C2) and the C2 cells were mainly of tumor origin." (PMID 36483553, 2022). "Tregs are believed to suppress the excessive immune response by expressing cytotoxic T-lymphocyte associated protein 4 (CTLA4) and secreting IL-10 and transforming growth factor beta (TGFβ), thereby promoting the immune escape of tumor cells." (PMID 35433424, 2022). "combined tumor vaccines with PD-1/CTLA-4 blockage to successfully improve the activity of effector T cells in mouse tumor cells, weaken the inhibitory effect of T-reg and strengthen the therapeutic effect of PD-1/CTLA-4 blockage." (PMID 36160005, 2022). "Tumors from mice treated with CTLA4-TβRII trap displayed higher proportions of 1) tumor reactive CD8+ IFNγ+ T cells, 2) CD4+ and CD8+ central memory T cells, and 3) lower percentage of FOXP3+ Tregs compared to control mice." (PMID 35577211, 2022). "In recent years, CTLA-4 inhibitors have also proven to be successful in tumor immunotherapy in clinical trials." (PMID 36466873, 2022). "We previously reported that a peri-tumor injection of low-dose hydrogel-encapsulated anti-CTLA-4 produced anti-tumor responses that were equal to, or better than, systemic dosing despite a >80% reduction in total dose." (PMID 35621582, 2022). "ICIs can modulate the tumour immune microenvironment through FcγR-dependent mechanisms, as mentioned for anti-CTLA-4 mAbs and depletion of Treg, or anti PD-L1 avelumab and myeloid subset composition." (PMID 35814459, 2022). "Activation of CTLA-4 and PD-1 can influence the proliferation of tumor-specific T cells and thereby protecting tumor cells in the TME." (PMID 36046747, 2022). "Loss or inhibition of CTLA-4 resulted in decreased Tregs function, and anti–CTLA-4 antibodies promoted anti-tumor activity by selectively reducing intratumoral Tregs." (PMID 36225938, 2022).
tumor (continued). "By synergizing with anti-CTLA-4, this platform suppressed tumor progression, prevented metastatic development, and promoted the development of immunological memory." (PMID 35568916, 2022). "Another outstanding finding was the induction of systemic antitumor response after intratumor Treg depletion with a mAb targeting CTLA-4 molecule, underscoring the relevance of Tregs as immunosuppressive mechanisms in tumor settings." (PMID 36059465, 2022). "MUC1 mRNA nanovaccine and anti-CTLA-4 mAb resulted in a significantly greater level of apoptosis in tumor cells when compared with PBS control group." (PMID 34875483, 2022). "The tumor inhibitory effects were found to be further improved by the combination of the anti-PD-L1 and anti-CTLA-4 antibodies, leading to significantly improved survival compared to mice without treatment and PDT single treatment." (PMID 35974207, 2022). "As expected, in anti-CTLA-4 Ab melanoma treatment, MNs loaded with Mg microparticles delayed tumor growth, achieving superior substantial tumor inhibition and remarkably improved animal survival compared to MNs without Mg microparticles." (PMID 35547773, 2022). "CTLA-4-disrupted cytotoxic T lymphocytes exhibited a pronounced anti-tumor effect in vivo in the subcutaneous xenograft BC model, making a rationale for CTLA-4 targeting in clinical trials." (PMID 36294884, 2022). "The most comprehensive exploration immune checkpoints PD-1, PD-L1 and CTLA-4 are crucial factors that inhibit tumor T cell immunity, and high expression of these molecules had a depressing outcome." (PMID 35227235, 2022). "Mice treated with P407 hydrogel-based multi-round PDT combination with anti-CTLA4 antibodies exhibited a comparable extent of tumor growth inhibition." (PMID 35974207, 2022). "PD-1, PD-L1, CTLA-4 are the main immune checkpoint receptor genes, which are mainly expressed in activated T cells and various tumor cells, while at the same time inhibit the activation of T cells and participate in the regulation of T cell function." (PMID 36147250, 2022). "A higher tumor TIDE prediction score is associated with worse ICB response as well as worse patient survival receiving anti-PD1 and anti-CTLA4 therapies." (PMID 36189319, 2022). "To better understand the association between metabolic alterations and ICB responses, we performed untargeted metabolomics of plasma samples from B16-F0 tumour-bearing mice with vehicle or ICB (anti-PD1 plus anti-CTLA4) treatment." (PMID 36109526, 2022). "Studies on bladder cancer cells indicated that inosine enhanced the function of anti-CTLA-4, causing to increase infiltration of IFN-γ+ CD4+ and IFN-γ+ CD8+ T-cells into the tumour, as well as reducing overall tumour weight." (PMID 36144335, 2022). "Commonly known checkpoints include PD-L1 on tumor cells as well as PD-1 or cytotoxic T-lymphocyte antigen 4 (CTLA-4) on T cells." (PMID 35053603, 2022). "This has turned out to be the case for certain tumor types and the anti-CTLA4 antibody, ipilimumab, has been FDA approved for the treatment of metastatic melanoma." (PMID 35814431, 2022). "Two anti-CTLA-4 agents, tremelimumab and ipilimumab, have been developed and used in many tumor types." (PMID 35799609, 2022). "Immunity checkpoint blockade with monoclonal antibodies targeting the B7-CD28 superfamily (CTLA-4, PD-1, and PD-L1) produces a durable anti-tumor immune response, and this strategy has been applied in many tumors and translated into clinical benefits." (PMID 35000592, 2022). "Higher protein expression levels of surface proteins OX40L and CTLA4 and lower expression of CD11c were detected in tumor adjacent stroma as compared to tumor epithelium." (PMID 36230846, 2022). "Some studies also observed that anti-CTLA-4 improves mice survival or represses tumor growth with the CT26 model." (PMID 35339889, 2022).
tumor (continued). "To explore mechanism of GIMAP4 underlying tumor-immune regulation, we calculated the correlations between GIMAP4 and 5 ICPs (CD274, CTLA4, TIGIT, LAG3, and PDCD1) and identified similar trends in their expression." (PMID 36246963, 2022). "PD1/PD-L1 and CTLA-4 are involved in the immune escape from tumors and are immune checkpoints for immune escape, when a tumor antagonizes, blocks, and suppresses the body's immune response through its structural and nonstructural products." (PMID 36105715, 2022). "Their research focused on blocking the inhibitory effects of CTLA-4 with a monoclonal antibody, leading to enhanced anti-tumor immune responses." (PMID 36295867, 2022). "The results from this clinical study suggest the importance of combined application of anti-CTLA-4 monoclonal antibody, anti-PD-1-PD-L1 monoclonal antibody, and radiotherapy, which activate the anti-tumor responses in multiple mechanisms." (PMID 35371055, 2022). "In our study, we found a tumor suppressive effect of a combination of low dose anti-PD-1 and -CTLA-4 antibodies (100 μg/injection x 3 for each antibody, 3 days apart) in the same mouse model." (PMID 35514996, 2022). "PD-1 and CTLA-4 can bind to ligands on tumor cells, thereby inhibiting the immune response mediated by T cells." (PMID 35178106, 2022). "Immunohistochemistry of human HNSCC tumours confirmed CTLA4 expression of on average 15.3% of excluded CD8+T cells." (PMID 35479076, 2022). "In the context of tumor immunoregulation, CTLA-4 acts in the early stage of T-cell response in the lymph nodes, as its ligands are mainly expressed on APCs." (PMID 36648843, 2022). "Most importantly, the combination of A2aR antagonists and anti-CTLA-4 therapy significantly restricts tumor growth and enhances the antitumor immune response." (PMID 36159861, 2022). "As we did not detect increases in PD-1 levels on T cells upon infection of tumours, we instead focused on elucidating the potential immunosuppressive role of CTLA4 in the TME due to its relevance in CRC." (PMID 36405739, 2022). "Inhibitory antibodies against CTLA-4 and PD-1 were first reported to have anti-tumor effects in preclinical studies in 1996 and 2002, respectively." (PMID 34811710, 2022). "More importantly, FCGR3A expression positively correlated with immune checkpoint molecules, including PD1, PD-L1, PD-L2, CTLA4, LAG-3 and TIM-3, and tumor-associated macrophage (TAM) gene markers in LGG." (PMID 39280892, 2022). "Goff and colleagues combined Newcastle disease virus, anti-PD-1 and anti-CTLA-4 with radiation to achieve significant tumour freedom, which was largely due to 20 Gy radiation exposure." (PMID 34561555, 2022). "Similar effects were observed in C57BL/6 mice treated with Panc02 (pancreatic cancer cell line), where CD47 mAb in combination with CTLA‐4 treatment inhibited tumour growth more profoundly than single treatment." (PMID 35908284, 2022). "The expression differences of immune checkpoints (PD-1, PD-L1, CTLA-4) in the three clusters and the expression differences between the tumor and normal tissues were explored." (PMID 35237659, 2022). "By contrast, CTLA-4 blockade facilitates priming of naïve tumor specific T cells or reactivation of memory cells by DCs in secondary lymphoid organs." (PMID 36175961, 2022). "Checkpoint inhibitors act on either the PD1/PD-L1 axis or CTLA-4 on T cells which reduces the interaction between cancer cells and immune effector cells, preventing the tumor cells from immune escape." (PMID 35804950, 2022). "Blocking CTLA-4 and PD-1 has been shown to reverse T cell exhaustion following chronic presentation of tumor antigens, leading to tumor killing." (PMID 35205732, 2022). "CTLA-4 blocker therapy, despite documented activities in concomitant activation, can also deplete regulatory T cells (Treg) from the tumor microenvironment (TME) as a result of high CTLA-4 expression at the Treg level." (PMID 35392976, 2022).